RAD51 (RAD51 recombinase)
Diseases named in the same sentence as RAD51 in open-access papers (continued):
Sharing a sentence is not in itself a finding about the gene and the disease.
tumor (continued). "Using this protocol, we were not able to visualize RAD51 foci in diagnostic FFPE tumor specimens that matched RECAP specimens with abundant numbers of RAD51 foci (RECAP-HRP cases), although sufficiently high endogenous DNA damage levels were present." (PMID 34203855, 2021). "The RAD51 mRNA levels analyzed in CRC samples from 48 patients undergoing surgery and without preoperative chemotherapy were upregulated in 2.5-fold compared to non-tumor tissue and associated with T stage." (PMID 34201502, 2021). "Likewise, the only one IDH1 mutant tumor in our dataset had low RAD51 levels, while the patient with equivocal IDH1 staining had relatively high RAD51 levels." (PMID 34771522, 2021). "In addition, we performed a side-by-side comparison of FFPE tumor specimens with matched specimens for which HR status was determined using a RAD51-based test that required ex vivo irradiation of fresh tissue (RECAP test)." (PMID 34203855, 2021). "An analysis of the subcutaneous tumours showed substantially reduced Ki67 staining and RAD51 protein abundance but increased cleaved caspase 3 and γH2AX protein levels in mice in the combination treatment group compared with mice in the monotherapy and control groups." (PMID 34761497, 2021). "Next, we generated a multivariate Cox proportional hazards (CPH) model that included the expression levels of POLD1 and RAD51 and other common clinical prognostic factors (patient age, KPS group, tumor size, extent of resection, IDH mutational status, and MGMT promotor methylation status)." (PMID 34771522, 2021). "The authors speculate that high levels of RAD51 promote a yet unknown immune checkpoint preventing T‐cell infiltration into the tumor." (PMID 33779077, 2021). "Furthermore, RAD51 overexpression positively correlates with tumor grading in IDC, but an inverse relationship was found with estrogen-receptor status." (PMID 33662042, 2021). "RAD51 expression was higher in tumor cells than in normal mucosal tissues." (PMID 32190537, 2020). "Likewise, functional assays are being developed to measure the ability of tumor tissue to actively produce RAD51/DNA foci as an indication of HRR efficiency." (PMID 33196706, 2020). "Finally, it converted SSBs into DSBs and impelled cell death in HR-deficiency tumor, for example BRCA1/2 mutations, RAD51 deficiency." (PMID 33628188, 2020). "The authors identified Rad51 and Rad51D as key targets of miR-103 in tumor cells." (PMID 33317198, 2020). "It will be important to determine whether modulating a specific RAD51 activity (i.e. protomer interactions, DNA binding, etc.)will be more clinically efficacious and in which tumor types it will benefit most." (PMID 33015624, 2020). "Furthermore, RAD51 expression is apparent in replicating (tumor lines) or quiescent (contact-inhibited primary astrocytes/MEFs) PTEN-deficient lines." (PMID 33138032, 2020). "However, for the SG-poorly-responsive MDA-MB-231 tumor line, Rad51 levels rose greater than 2-fold within 24 h of SG exposure." (PMID 33196706, 2020). "A major advantage of this approach is that RAD51-based tests detect the current HR status of the tumor, irrespective of underlying genetics." (PMID 33003546, 2020). "Moreover, inhibition of AKT-signaling attenuated co-localization between Rad51 and γ-H2AX foci after Dox treatment, thus suggesting a failure in the recruitment of Rad51 to DSBs in AKT-inhibited tumor cells after Dox treatment." (PMID 33266502, 2020). "In two PDX cases (PDX1 and PDX9), miR-509-3 could significantly increase the sensitivity to Olaparib along with the decrease of RAD51 positive rate (mean tumor weight NC + Olaparib vs. miR-509 + Olaparib; PDX1 P < 0.05, PDX9 P < 0.05)." (PMID 32005272, 2020). "Given the simultaneous inhibition of BRCA1 and RAD51, the combination of BET inhibitors with PARP inhibitors may further increase the sensitivity of HR deficient, BRCA mutated tumor cells by further downregulating expression of RAD51." (PMID 32180937, 2020).
tumor (continued). "Also, RAD51 overexpression can lead to the enhancement of cell growth inhibition and apoptotic induction, resulting in tumor progression." (PMID 32190537, 2020). "Allele XRCC3-241Met (OR 0.85, 95%CI 0.72–0.99, p < 0.045), XRCC2-41657 T (OR 1.67, 95% CI 1.42–1.96, p < .0001), BRCA1-356R (OR 1.61; % CI 1.37–1.90, p < .0001) and RAD51–135C (OR 5.16; 95% CI 4.29–6.20, p < .0001) strongly correlated with the neoplastic disease." (PMID 30712190, 2019). "In our study, we observed the downregulation of RAD51 in tumor samples, which may account for the RAD51AP1 increase." (PMID 31159852, 2019). "In summary, we demonstrate the feasibility of the RAD51 assay in routine FFPE tumor samples and its utility to identify several populations that might be sensitive to PARPi." (PMID 30377213, 2018). "Similarly, the RAD51 antibody mainly stained tumor cell cytoplasm; only two samples showed predominant RAD51 cytoplasmic staining with some nuclear staining of tumor cells." (PMID 29673125, 2018). "HR is involved in tumor chemo-resistance, and RAD51 plays a primary role in this pathway." (PMID 29670086, 2018). "Targeting RAD51-dependent repair is known to enhance tumor cell radiosensitivity." (PMID 30282933, 2018). "In addition, immunohistochemical staining of mouse tumor tissue slices revealed that melatonin significantly inhibited expression and nuclear transport of RAD51 in tissues." (PMID 30201872, 2018). "RAD51 is a key protein in the repair pathway for DNA double-strand breaks; it has been shown to be critical to the homologous recombination repair process in cells and can be employed as a mechanism of resistance to DNA-damaging agents in tumor cells." (PMID 29113403, 2017). "The combination of RAD51 KD and PARPi led to a more robust inhibition of tumor growth." (PMID 28359295, 2017). "We also observed a remarkable reduction in RAD51 in tumor xenografts in berberine-treated hosts." (PMID 28981112, 2017). "In the present study, we observed downregulation of RAD51 in hypoxic Calu-6 tumor cells in vivo." (PMID 27020103, 2016). "Additionally, data from immunohistochemical (IHC) assays showed that RAD51 was also dramatically reduced in (−)-Guaiol treated tumor tissues." (PMID 27566579, 2016). "We found an elevation of Rad51 expression in 45% of tumor specimen (13 patients)." (PMID 27074032, 2016). "Next, data from immunostaining assays showed that both LC3 II and γH2AX were reduced in RAD51 overexpressed A549 cells treated with (−)-Guaiol, indicating that (−)-Guaiol inhibited tumor growth by targeting RAD51 for lysosome degradation to induce DSBs-triggered cell apoptosis." (PMID 27566579, 2016). "And deletion of Rad51 gene would sensitize tumor cells to chemotherapeutic agents." (PMID 26752698, 2016). "Given our results using artificial induction of high levels of RAD51 in S33 cells, we reasoned that spontaneous RAD51 foci observed in other tumor lines might involve binding of the protein to undamaged DNA." (PMID 25765654, 2015). "Thus, the concentration of RAD51 in the human tumor cells examined here exceeds that required for direct binding to dsDNA in vitro." (PMID 25765654, 2015). "BRCA2 and the Rad51 paralogs are tumor suppressors and critical mediators of Rad51." (PMID 26186187, 2015). "RAD51 steady-state levels are elevated in a wide variety of tumor cells." (PMID 25765654, 2015). "Although speculative, this list could include other key HDR genes including ATM, BRCA1/2, MRE11, RAD50, NBS1 or RAD51, which are also mutated in CRC and many other tumor types." (PMID 26318585, 2015). "Intriguingly, many tumor lines with elevated RAD51 display spontaneous RAD51 foci." (PMID 25765654, 2015). "Overall tumour burden median was lower in the RAD51 depleted cohort compared to the control cohort." (PMID 24811120, 2014).
tumor (continued). "We further wished to investigate whether inhibition of RAD51 would increase the anti-tumor activity of cisplatin invivo." (PMID 24971740, 2014). "Additionally, 46 of 53 (86.7 %) cases without NACRT presented diffuse staining patterns from the shallow to deep levels of the tumor nest, with the expression pattern of Rad51 appearing homogenous." (PMID 24065387, 2014). "Notably, RAD51 is highly expressed in matched lymph node and brain metastasis compared to primary tumor." (PMID 24811120, 2014). "The suggested progression-promoting effect of mutated BAP1 is in line with the tumor suppressive function of intact BAP1 as a deubiquitylase required for efficient assembly of the homologous recombination (HR) factors BRCA1 and RAD51 after DNA double-strand breaks (DSBs)." (PMID 25593912, 2014). "Interestingly, increased expression of the RAD51 protein has been reported in immortalized and tumor cells and its link to the genomic instability observed in these cells has been established." (PMID 24319145, 2014). "We propose that HLTF might restore the continuity of the gapped DNA by a RAD51-independent mechanism and this may help to explain its possible tumour-suppressor properties." (PMID 24198246, 2014). "One can speculate that assessment of RAD51 depletion in tumor cells after two or three days of combined treatment might be useful for early prediction of tumor responses in NPC patients." (PMID 24618637, 2014). "Therefore, the problem of genetic variability of the RAD51 gene for tumor development is worth to be studied." (PMID 24930116, 2014). "Reduction of RAD51 combined to enhanced detection of EBER 1 might be helpful for early assessment of tumor response." (PMID 24618637, 2014). "Because the Rad51 staining pattern was homogenous in the majority of cases, the expression pattern of biopsy specimens was considered to reflect the Rad51 expression status in the whole tumor nest." (PMID 24065387, 2014). "A natural assumption therefore is that the high levels of Rad51 expression seen in tumour cells reflect the protein’s role in DNA repair; in other words, that Rad51 may act as a tumour suppressor." (PMID 23795299, 2013). "In general, Rad51 is expressed at higher levels in tumor cells as compared with normal cells." (PMID 26316936, 2012). "The level of the Rad51 protein is elevated in some tumor cell lines." (PMID 26316936, 2012). "The analysis correlating focus formation of BRCA1, γH2AX, and Rad51 prior to treatment and of Rad51 foci after EC treatment with the mean tumor volume reduction or tumor response rate uncovers a significant inverse correlation with tumor response for each of the four conditions." (PMID 20205718, 2010). "A number of approaches have shown that reduction in Rad51 levels via antisense oligonucleotides, ribozymes or drugs increased the radiation sensitivity of tumour cell lines." (PMID 15785736, 2005). "Additionally, stratified survival analysis by histological tumour cell type demonstrated that Rad51 expression was closely related to the survival of both lung SCC and lung ADC." (PMID 15956972, 2005). "Furthermore, Rad51 overexpression correlates with histological grading of the tumour in invasive ductal mammary carcinoma." (PMID 15956972, 2005). "Importantly, Rad51 expression (P<0.0001) together with tumour differentiation (P<0.009), clinical stage (P=0.004) and N status (P=0.0001) proved to be independent prognostic parameters in multivariate analysis." (PMID 15956972, 2005). "More importantly, downregulation of Rad51 protein by Rad51 RNAi technology or Rad51-inhibitory drugs could be used to sensitise tumours to radiation or chemotherapy." (PMID 15956972, 2005). "Rad51 protein is highly expressed in tumour cell nuclei of several solid carcinomas." (PMID 15956972, 2005).
tumor (continued). "We hypothesise that the decreased survival of NSCLC patients with high-level expression of Rad51 is related to an enhanced propensity of tumour cells for survival, antiapoptosis and chemo-/radioresistance." (PMID 15956972, 2005). "Furthermore, pathways involved in xenobiotic metabolism (GSTs, DHDH, AKR7A2, HSD11B1L, CYP1B1, UGTs), drug metabolism, nucleotide metabolism, and homologous recombination (RAD51) reflect the tumour’s ability to adapt to environmental stressors and resist therapy." (PMID 41007296, 2025). "More recently, 3E10 was found to bind RAD51 and to be synthetically lethal in BRCA2- and PTEN-deficient cells, and new pre-clinical studies have also demonstrated the ability of 3E10 to deliver nucleic acids into tumor cells (with functional release) following systemic administration." (PMID 39352803, 2024). "Since prior work has shown that the lower affinity chimeric WT 3E10 has a higher affinity interaction with purified RAD51, we hypothesized that, like cellular penetration and tumor localization, nucleic acid affinity could be predictive of RAD51 binding efficiency." (PMID 39352803, 2024). "Thus, the role of Rad51 in the EMT program of tumor cells has also been studied." (PMID 35875146, 2022). "Therefore, Rad51 mediates tumor metastasis through multiple mechanisms, which may provide new therapeutic targets for overcoming tumor progression." (PMID 35875146, 2022). "Low RAD51 foci scores were associated with longer median rPFS (9.3 vs. 2.9 months) and OS (17.4 vs. 9.5 months) compared to high RAD51 scores amongst olaparib sensitive tumours; however, low RAD51 scores did not capture all potential responders." (PMID 36497408, 2022). "Consequently, RAD51 is not included in genetic diagnostic tests or in screening for tumour chemotherapy response." (PMID 34316706, 2021). "Whether restoration of RAD51 foci formation is a key mechanism of acquired PARPi resistance in the clinic still remains to be addressed and is challenging due to limited post-PARPi tumour biopsies." (PMID 35008208, 2021). "After the administration of both VPA and IR, tumor growth was significantly inhibited comparing to IR alone (P < 0.01), the DSBs detected by γH2AX was enhanced, the protein level of Rad51 was inhibited, but RFWD3 protein level was increased as compared with IR treatment alone." (PMID 33842359, 2021). "However, the positive presence of RAD51 proteins might be informative, as a sign that the tumor is HR-proficient." (PMID 32192091, 2020). "Furthermore, RAD51 can protect tumor cells from radiation-induced damage." (PMID 32190537, 2020). "However, if the tested cell lines accurately model the relevant tumor tissues, the lower sensitivity of RAD51 paralog mutants to PARP inhibitors may predict a reduced clinical response in tumors with the corresponding gene defects." (PMID 31727117, 2019). "Quantification of RAD51 mRNA by RT-qPCR showed, in line with protein data, lower levels in patients exhibiting complete response to treatment (pR0) compared to patients with macroscopic residual tumor (pR2), difference approaching statistical significance (p=0.07)." (PMID 29212225, 2017). "In contrast to FA, HR factors including RAD51, RAD51 paralogs and BRCA2 are required for telomere replication and capping and thus the genomic instability characteristic of HR‐deficient cells and tumours may have a telomere dysfunction component." (PMID 27037238, 2016). "In the near future, the systematic evaluation of PAR levels, γH2AX, FANC and RAD51 foci with genomic instability features in tumor biopsies before, during and after treatment might help to identify patient populations who can be classified as responders or non-responders to PARP inhibitors." (PMID 27884198, 2016). "Collectively, oleandrin may be a potential anti-tumor agent by suppressing the expression of Rad51." (PMID 27449097, 2016).
tumor (continued). "Finally, our data with patient derived mutants of RAD51C uncover the tumor suppressor function (s) of RAD51 paralogs, at least in part mediated by suppression of replication associated damage and promotion of timely restart to avoid error prone repair mechanisms." (PMID 26354865, 2015). "Thus, in addition to its genome stabilizing DNA repair activity, RAD51 may also promote tumor progression in tumors where RAD54 activity is limiting." (PMID 25765654, 2015). "It seems likely that the sensitivity of BRCA defective tumour cells to PARP inhibitors is caused by their characteristic defect in repair of DNA double strand breaks (DSBs) by homologous recombination (HR), a process controlled by BRCA1, BRCA2 and the DNA recombinase RAD51." (PMID 25883215, 2015). "Thus, assessment of whether the relapsed tumor cells restore HR function, for example, using DNA sequencing and Rad51 foci formation assays, could be key to determining the sequential treatment strategies." (PMID 25158060, 2014). "Indeed, the body weight of nude mice is not affected by Rad51 inactivation via daily IBR2 treatment, and IBR2 has no significant inhibitory effect on CD34+ normal bone marrow cells, suggesting that inhibition of RAD51 can be tumor-selective to a certain extent." (PMID 23341130, 2013). "Thus, RAD51 is an attractive target molecule for developing tumour-selective inhibitors." (PMID 23341130, 2013). "However, the induced expression of Rad51 within a tumor cell may reduce the cell's sensitivity to subsequent irradiations." (PMID 26316936, 2012). "Rad51 could serve as a prognostic marker to improve tumour classification of NSCLC." (PMID 15956972, 2005). "Regarding the tumor dose effect, previous findings have indicated that both HepG2 and HepG2R cells upregulated the DNA HRR protein RAD51 at 24 h following 2 Gy BA-BNCT irradiation." (PMID 40824344, 2026). "This in turn reduced RAD51 expression, leading to an accumulation of DNA damage, decreased cell viability and reduced OCCC tumor growth." (PMID 41933240, 2026). "In summary, RAD51, TIMELESS, RFC3, and TONSL converge on pro-proliferative pathways that sustain tumor survival and expansion." (PMID 41179682, 2025). "The assembly of RAD51 filaments is tightly regulated by tumor suppressors, most notably the BRCA2-PALB2 complex and the RAD51 paralogs (RAD51B, RAD51C, RAD51D, XRCC2 and XRCC3)." (PMID 41196948, 2025). "In luminal B tumours, our analyses show genes such as TP53I11 and RAD51 correlate with better prognosis through enhanced apoptosis and homologous recombination repair (HRR), respectively." (PMID 41007296, 2025). "Consistent with the in vitro findings, we observed increased RAD51 chromatin accumulation and reduced γH2AX levels in CDXE-resistant tissue-isolated tumor cells, indicating that hyperactivated DNA repair mitigated DNA damage." (PMID 40634292, 2025). "In the study mentioned, a strong correlation was found between high RAD51 expression and KELIM scores in pre-NACT tumor tissues and platinum resistance recurrence." (PMID 41199843, 2025).